IFNG (interferon gamma)
Diseases named in the same sentence as IFNG in open-access papers (continued):
Sharing a sentence is not in itself a finding about the gene and the disease.
infection (continued). "Interestingly, on day 14 post-infection, the levels of IL-12 and IFNγ were significantly higher in HPIV3/full S group compared to all other groups." (PMID 35468973, 2022). "The Th1 profile produces cytokines such as interferon-gamma (IFN-γ), tumor necrosis factor (TNF), and interleukin 2 (IL-2), which are associated with the control of infection by macrophages, the production of nitric oxide (NO), and the consequent destruction of intracellular parasites." (PMID 35844611, 2022). "Its main function is removing infection and cleaning the cellular matrix debris from foreign substances binding antigens, then it will be activated to secrete lymphokines, one of which is interferon gamma (IFN-γ)." (PMID 34491461, 2022). "Using qPCR to compare the expression of Ifnγ in the gastric antrum from mice infected with wild-type vs. ΔCagE PMSS1, we found that expression is significantly higher in wild-type-infected animals, indicating that the strong induction of Ifn-γ expression upon infection requires the T4SS." (PMID 35332152, 2022). "Infection of airway epithelial cells by SARS-CoV-2 causes cytological damage by activating the local immune response, releasing proinflammatory mediators such as IFNγ, IL-1β, IL-6, TNF-α." (PMID 36012968, 2022). "In our study, adaptive cytokine responses, as indicated by IFNγ, IL-2 and the IFNγ−inducible chemokine IP-10, were elevated in individuals with any prior exposure to C. burnetii, whether through vaccination or infection." (PMID 35812430, 2022). "We further examined whether IFNG- and IFNGR1-knockout cell lines show enhanced susceptibility to infection by different types of viruses besides HSV-1." (PMID 35897807, 2022). "Moreover, it was shown that the cytokine IL-12 is playing an important role for adequate IFNγ production during infection." (PMID 36430676, 2022). "However, the percentage of IFNγ+ CD8+ T cells after α-CD3 stimulation was only slightly increased after PICV infection in both LCMV groups, compared to the respective group prior to PICV infection, reaching no significance." (PMID 36298848, 2022). "Similarly, while holding day constant, infection status maintained a significant influence on Ifnγ, Il1β, Il10, and Cox2 abundance (p ≤ 0.0273), with tendencies for Tnf and Cox1 (p = 0.0569 and p = 0.0645, respectively)." (PMID 35312688, 2022). "Importantly, IFNγ+ T-cell responses three months after vaccination were comparable to those at three, six, and twelve months after infection (mean SI 11.8 ± 1.4, 13.5 ± 1.7, 12.8 ± 3.0, 11.3 ± 1.3, respectively)." (PMID 34960185, 2021). "Conversely, ITT sheep, which are resistant to F. gigantica and susceptible to F. hepatica, demonstrate a less dominating IL-4/IFNγ ratio and elevated IgG2 levels when displaying resistance against F. gigantica 10 weeks post-infection, compared to during a F. hepatica infection." (PMID 34207215, 2021). "In case of DENV-2, significant upregulation in IL-12 (p<0.05) and IFNγ (p<0.05) was observed in primary infection than secondary; while GM-CSF (p<0.0001) and IP-10 (p<0.01) were upregulated in secondary than primary infection." (PMID 34447698, 2021). "Overall, it is likely that IFNγ may play a role in ameliorating E. coli colonization, infection or recovery; future studies examining the site-specific responses of IFNγ are necessary." (PMID 33963240, 2021). "Interestingly, GM-CSF and IFNγ show counterexpression in all serotypes during primary and secondary infection." (PMID 34447698, 2021). "This is in line with recently published studies, demonstrating the crucial role of TIM-3 over-expression on T cells in the control of infections with intracellular bacteria such as Mycobacterium tuberculosis, where IFNγ mediated immune effector pathways play a decisive role." (PMID 34108960, 2021). "To test whether IDO1 was functional, we performed a UHPLC–MS/MS analysis of the uninfected/untreated and infected and/or IFNG treated HL-60 and HeLa cells at 24 h post-infection." (PMID 34819931, 2021).
infection (continued). "After 4 h we could detect the first signs of increasing amounts of IFNγ following the infection of a single renal tubule." (PMID 34015044, 2021). "Infection with the PtdSerpos subpopulation of T. gondii inhibits NO production by activated macrophages, an effect that in vitro has been described to be caused by the engagement of the PtdSer receptor TIM-4 in the context of LPS and IFNγ stimulation." (PMID 34279684, 2021). "IL-6, IL-12, IL-8, interferon-gamma, and IL-1β all show increased secretion 48 hours after infection; however, the greatest (and most statistically significant) increase is shown by IL-6 equating to a fourfold increase above that of the uninfected control 48 hours postinfection." (PMID 34152044, 2021). "Lastly, we identified IFNγ as a key antiviral cytokine in survival following CCHFV-infection." (PMID 33572859, 2021). "Additionally, IL-6 is critical for differentiation and maintenance of IL-23 dependent TH17 cells- important for recruitment of neutrophils to infection site, and IFNγ mediated control of M tuberculosis." (PMID 33995365, 2021). "Y. pseudotuberculosis also directly subverted a human Vδ2+ T cell IFNγ response, suggesting that this pathway may function similarly in human infection to aid Y. pseudotuberculosis pathogenesis." (PMID 34871329, 2021). "Consistent with a previous study in this cohort, ex-vivo ELISPOT assays using peptide pools representing all four DENV serotypes detected overall low frequencies of IFNγ-secreting cells prior to symptomatic secondary infection and inconsistent increases in these responses after infection." (PMID 34394112, 2021). "Moreover, the relative numbers of IFNγ-producing Th17-like and Tfh-like cell subsets were decreased in patients with moderate and severe infections." (PMID 34696395, 2021). "In contrast, IL-18 only slightly induces IFNγ after low dose of infection." (PMID 34938670, 2021). "Given this, we next determined whether clearing women had higher local levels of IFNγ illustrative of a more robust immune response, compared to women with persisting infection." (PMID 33912473, 2021). "Moreover, infection with T. gondii promotes stromal cells to produce IL-33, which synergizes with IL-12 to amplify IFNγ production by ILCs for protection." (PMID 34938670, 2021). "Therefore, continuous systemic Th1 immune response, crucially IFNγ, is necessary to control T. gondii parasitism in the brain in the chronic phase of infection." (PMID 34610039, 2021). "Although IFNγ produced by NKp46+RORγt+ ILCs contributes to bacterial clearance, it can also induce epithelial damage, as Tbx21-/- and Ifngr1-/- mice displayed reduced intestinal pathology 48h after infection." (PMID 34938670, 2021). "Ifnγ expression by Th22 subsets questioned whether SFB induces Th1 cells that are able to secret IL-22 upon infection." (PMID 34566952, 2021). "However, IFNγ from ILCs can also induce mucus production and impair tight junction during infection, potentially leading to an additional tissue damage." (PMID 34938670, 2021). "However, although they were able to induce specific anti-SARS-CoV-2 reactive cells upon infection, the level of S1 antigen-induced interferon-gamma release during the convalescent phase was significantly lower than that observed for HD patients." (PMID 34768356, 2021). "Consequently, it appears that the variation in the IFNG system is involved in both the outcome of infection and pathology." (PMID 33659002, 2021). "We find that 2 weeks post infection, the host through an interferon gamma (IFN-γ) mediated mechanism upregulates its histidine catabolizing enzymes – histidine ammonia-lyase (HAL) and histidine decarboxylase (HDC), possibly to starve the Mtb of free intracellular histidine." (PMID 33767335, 2021). "Surprisingly, these activated T-cells were deficient in their ability to produce IFNγ, perhaps providing a reason why the infection is not completely cleared." (PMID 35186781, 2021).
infection (continued). "GM-CSF inhibits IFNγ via STAT1; this might be the reason for low IFNγ in secondary infection, which needs to be studied." (PMID 34447698, 2021). "Both cytokines are important in defense against SFG as well as TG rickettsiae and orientiae, whereby IFNγ may play a more critical role in the infection with SFG and transitional rickettsiae." (PMID 34452021, 2021). "Regarding the inflammatory cytokine contents in mice after infection, the contents of TNFα, IFNγ, IL-1β, and IL-18 in serum, spleen, and ileum of mice challenged with ΔhtpG strains were significantly decreased (p < 0.05) as compared with mice challenged with WT strains." (PMID 34869065, 2021). "Together these data support the RNAseq results and suggest that RMT-iRBCs trigger a stronger myeloid and IFNγ-dependent inflammatory response in the spleen that may be important in attenuating P. chabaudi RMT infections." (PMID 34532703, 2021). "The findings revealed an upregulated expression of IFNG in the treated group during the infection." (PMID 34438767, 2021). "While the percentage of participants that mounted a T-cell response were also comparable at three months after vaccination and infection (87% and 89%, respectively, for IFNg+ T-cell responses), responses at six and twelve months post-infection were lower at 80% and 75% of participants, respectively." (PMID 34960185, 2021). "IFNγ-mediated MHCII is required for the effective host response against infections." (PMID 34747695, 2021). "Our results indicate that in O. mykiss, the oral administration of rIFNγ-producing L. lactis (MT009) stimulates the expression of genes that participate in the IFNγ-mediated response at the systemic level, producing a state of protection against infection of extracellular bacterial pathogens." (PMID 34248997, 2021). "Not only IFNγ impact the BM, other cytokines that are produced by Mφ, such as IL-6, TNF and type I IFN, have been also associated with disturbances in BM precursors after infection and/or inflammation." (PMID 34987496, 2021). "However, excessive production of IL-18 by epithelial cells after infection with high dose of T. gondii contributes to intestinal pathology by inducing IFNγ." (PMID 34938670, 2021). "Additionally, APCs secrete IL-12, IL-15, and IL-18, which stimulate IFNγ secretion at the infection site." (PMID 34938670, 2021). "Of note, upregulation of Ptgs2 expression and production of PGE2 were both potentiated by BMDM exposure to IFNγ prior to infection with Mtb, and the inhibitory effect of iFADS2 on Mtb-driven production of PGE2 production was maintained in IFNγ-activated macrophages." (PMID 34951591, 2021). "Together, these results showed that RMT P. chabaudi triggered an overall stronger and earlier innate and IFNγ-dependent immune response in the spleen, which could be responsible for the attenuation of the blood-stage infection." (PMID 34532703, 2021). "Furthermore, IFNγ-/- mice displayed a decrease in bacterial burden at the site of infection due to reduced CXC chemokine production and subsequent PMN recruitment." (PMID 34220813, 2021). "However, by day 3.5 post-infection, IFNγ expression was significantly higher in MCMV-Δm15 infected mice than in MCMV-Rev infected mice." (PMID 34358016, 2021). "In several models of infection including Lm, IFNγ is produced independently from cognate Ag, which further underscores the need to understand how cognate Ag may potentiate or contribute to IFNγ-mediated protection." (PMID 34516896, 2021). "In Northern Ireland, IFNγ is routinely used in herds with problems clearing infection." (PMID 33848298, 2021). "Thus, a new paradigm emerges that during mucosal pathogen infection, infiltrating Ly6Chi monocyte produces IL-12p70 or IL-18 that instructs NK cells or T cells to produce IFNγ." (PMID 34512626, 2021).
infection (continued). "IFNγ treatment reduced the bacterial load in the spleen to a modest level and almost completely in the liver of Il15-/- mice, suggesting that impaired early IFNγ production plays a crucial role in the control of the infection." (PMID 34956227, 2021). "Infection induces increased ILC production of IFNγ, and some begin to co-express GM-CSF." (PMID 33414524, 2021). "It is known that fully differentiated Th17 cells can deviate toward a Th1 phenotype, acquiring the ability to secrete IFN-γ, which can be useful for host defense against infections, as IFNγ may contribute to a protective response." (PMID 34925371, 2021). "After STM infection migratory ILCs express significantly higher levels of Ccl3, Gbp2, Gbp6, Irf1, Irf4, Irf7, Pml and Stat1, all of which are regulated in response to interferon gamma." (PMID 33414524, 2021). "We found that 63.9% of individuals showed IFNγ ex vivo T cell responses to the S1 pool of overlapping peptides, following a single dose of the vaccine, which is comparable to what was seen following natural infection." (PMID 34326317, 2021). "In our cohort, the levels of IFNγ measured were significantly below those needed to clear Ct infections in in vitro models, suggesting additional factors may be at work in vivo in women." (PMID 33912473, 2021). "In addition to attempting to control the infection, the production of IFNγ is related to neuronal decrease by inducing the production of nitric oxide via iNOS in an experimental model." (PMID 33561140, 2021). "Without a full understanding of the global mechanisms controlling IFNγ-mediated MHCII regulation in macrophages, it has proven difficult to dissect the mechanisms related to MHCII expression that cause disease or lead to infection susceptibility." (PMID 34747695, 2021). "Interferon-gamma (IFNγ) and tumor necrosis alpha (TNFα) are secreted by pro-inflammatory macrophages and are known stimulants of apoptotic pathways as a physiological mechanism in response to infection or injury." (PMID 34070547, 2021). "An IFNγ-dependent increase in PMN recruitment to the site of infection provided a PMN-rich environment in which S. aureus could survive more readily." (PMID 34220813, 2021). "Moreover, one of the significant roles of NK cells and CD4+ T lymphocytes in liver protection and infection control is interferon-gamma production (IFN-γ)." (PMID 34578107, 2021). "Infection of mice with Hpb causes greater intestinal damage if NK cells are either absent or unable to produce IFNγ." (PMID 34760351, 2021). "To test how IFNγ may modulate the inflammatory IL-8 and IL-6 responses from the epithelial cells, we added IFNγ into the medium of the biomimetic flow-chamber one hour before infection and measured the inflammatory response." (PMID 34015044, 2021). "However, IL-18 is produced by porcine DC-enriched PBMC following live tachyzoite infection, which, as we demonstrated, plays an important role in IFNγ induction by NK cells." (PMID 34576723, 2021). "Localized production of IFNγ by CD8+ T-cells within infected tissues may contribute to survival following infection and it is also possible that CD8+ T-cells contribute to control of CCHFV through targeted killing of infected cells." (PMID 33572859, 2021). "IFNγ is also elevated at the site of infection due to the host Th1 immune response." (PMID 34959539, 2021). "Inflammatory cells infiltrate the sites of infection at an early stage of the infection with SARS-CoV2 and cause a stormy release of pro-inflammatory cytokines like IL-6, IL-17A, TNFα, IFNγ, IL-1α/β, and chemokines like CC-chemokine ligand 2 (CCL2) as well as CXC-chemokine ligand 10 (CXCL10)." (PMID 33643316, 2021). "In cattle, pulmonary lesions associated with experimental M. bovis infection via aerosol have been noted as early as 15 days after infection and robust interferon-gamma (IFN-γ) responses to both complex and specific M. bovis antigens are seen 3 to 4 weeks after infection." (PMID 33166313, 2020).
infection (continued). "Finally, heightened induction of Gbp2, Gbp4, Gbp5, Gbp6, and Ip10 in Sts−/− cells relative to wild type cells was observed following both IFNγ treatment alone and LVS infection of IFNγ‐treated cells." (PMID 32841534, 2020). "Consistent with expectations, the CD27+ γδ T cells were the main producers of IFNγ after infection." (PMID 32636457, 2020). "However, vaccination of mice with Msm ΔespG3::mtp64 prior to Mav infection was found to increase the frequencies of IL-17-producing Th17, Tc17 as well as IFNγ/IL-17 double-producing CD4+ and CD8+ T cells." (PMID 32582196, 2020). "Studies of the mechanisms underlying CD4+ T cells roles in S. aureus infection indicate that IFNγ may be dispensable during primary infection, whereas the requirement for IL-17 varies depending on the infection model." (PMID 33291260, 2020). "Patients with unaltered IFNγ levels succumbed to the infection." (PMID 32012176, 2020). "However, after week 5 of infection, NK cells produced very little IFNγ while significantly increasing their CD107a expression." (PMID 32733814, 2020). "However, it is likely that this set of fitness-conferring genes varies by host cell type, host species, and after infection of IFNγ-activated cells." (PMID 33067458, 2020). "Therefore, we incubated MDMs with IFNγ (referred to as M1) prior to infection with HSV-1 to induce a more proinflammatory cell." (PMID 32101570, 2020). "Thus, infection of naïve and IFNγ-stimulated BMDMs modulated by differences in the induction of unique and common gene sets." (PMID 33014886, 2020). "In addition, there was attenuated intestinal tumor necrosis factor alpha (TNF-α) and interferon gamma (IFN-γ) responses during infection with the ΔcadF mutant compared to the wild-type strain." (PMID 32168837, 2020). "We next determined whether IFNγ was necessary to promote access of Salmonella or their LPS to the cytosol by quantifying bacterial resistance to CHQ at 1.5 h post-infection (p.i.)." (PMID 32581219, 2020). "By analysing cytokines associated with the major CD4+ve Thelper (Th) cell subsets (Interferon-gamma (IFN-γ)/Th1; Interleukin (IL)-4/Th2; IL-17A/Th17; IL-10/Tregulatory), we show that there is selective activation of PBMC producing IFN-γ and/or IL-10 during the latent phase following infection." (PMID 32487248, 2020). "The addition of IFNγ after infection not only resulted in a dramatic increase of the translation of the before mentioned genes but also in the translation of IFNß1, IL12ß, MIP1 and CCL3, CCL4, NOS2 and SOD2, and FAS but, nevertheless, did not prevent multiplication of the bacteria." (PMID 32462327, 2020). "In order to gain mechanistic insights of Tir-induced caspase-4 activation, we performed proteomics analysis of SNU-C5 cells following infection of unprimed and IFNγ-primed cells with EPEC-0, EPEC-2, EPEC-1-TirAA-EspZ, EPEC-1, and EPEC-1-TirAA, using isobaric labelling." (PMID 33378358, 2020). "In another study, it was shown that CD4+ T cells with an inducible regulatory phenotype (CD4+CD25+FoxP3-T-bet+CTLA4high) produced IFNγ and IL-10 in the infection of C3H/HeN mice with a lethal dose of R. conorii and that these cells suppressed proliferation and IL-2 release by CD4+ T cells in vitro." (PMID 33091016, 2020). "In murine infection models of this bacteria, a deficient immune response has been determined, not only for NK cells, but also for NKT cells and CD8+ T cells, due to decreased degranulation and IFNγ production." (PMID 33120910, 2020). "This is perhaps most simply illustrated by a clustered heatmap containing of a subset of the IFNγ response gene set, where infection by all strains and species results in increased transcript abundance but the magnitude of that induction is highly species-specific." (PMID 32574210, 2020).